OLFM4 (olfactomedin 4)
Diseases named in the same sentence as OLFM4 in open-access papers (continued):
Sharing a sentence is not in itself a finding about the gene and the disease.
Shock (3 papers, 2020 to 2025). The state in which profound and widespread reduction of effective tissue perfusion leads first to reversible, and then if prolonged, to irreversible cellular injury. "The gene OLFM4, previously associated with neutrophil subpopulations in pediatric septic shock, also has a strong association (p = 7.91e-15)." (PMID 41346599, 2025). "In our previous study in patients with septic shock, a high percentage of OLFM4+ neutrophils was associated with greater organ injury and death." (PMID 32470072, 2020). "This study was initiated because we previously showed patients admitted with septic shock and high percentage of OLFM4+ neutrophils had worse outcomes." (PMID 32470072, 2020). "OLFM4 and LTF were subpopulations of neutrophils in septic shock." (PMID 34692829, 2021).
triple-negative breast carcinoma (3 papers, 2019 to 2023). An invasive breast carcinoma which is negative for expression of estrogen receptor (ER), progesterone receptor (PR), and human epidermal growth factor receptor 2 (HER2). "MIR503HG inhibits cell migration and invasion via miR‐103/OLFM4 axis in triple negative breast cancer." (PMID 31062436, 2019). "Based on above results, we thought that MIR503HG inhibits cell migration and invasion via miR‐103/OLFM4 axis in triple negative breast cancer." (PMID 31062436, 2019). "The study in vitro suggested MIR503HG inhibits cell migration and invasion via miR‐103/OLFM4 axis in triple negative breast cancer." (PMID 31062436, 2019). "MIR503HG could inhibit migration and invasion of cells via miR-103/OLFM4 axis in triple negative breast cancer." (PMID 33176720, 2020). "Therefore, we had a hypothesis that MIR503HG inhibits cell migration and invasion via miR‐103/OLFM4 axis in triple negative breast cancer." (PMID 31062436, 2019). "Thus, we had a hypothesis that MIR503HG inhibits cell migration and invasion via miR‐103/OLFM4 axis in triple negative breast cancer." (PMID 31062436, 2019).
viral infections (3 papers, 2015 to 2025). "Olfm4 is expressed in high amounts in neutrophils and can serve as a biomarker for the severity of several bacterial or viral infections." (PMID 40684206, 2025). "Thus, other studies have also seen upregulation of OLFM4 expresion after bacterial or viral infection." (PMID 26162090, 2015). "Several genes in this group (CTSG, encoding the neutrophil serin protease Cathepsin G; DEAFA4, defensin alpha 4; LCN2, lipocalin 2; OLFM4, BPI and CD24), are known to be overexpressed in patients with severe viral infections, including COVID-197,14." (PMID 35181735, 2022).
Alzheimer disease (2 papers, 2015 to 2026). A progressive, neurodegenerative disease characterized by loss of function and death of nerve cells in several areas of the brain leading to loss of cognitive function such as memory and language. "This extended signature includes granule proteins CAMP, CTSG, DEFA3, and MPO secreted from neutrophils and points to olfactomedin 4 (OLFM4) as a new target for the prevention of Alzheimer's disease." (PMID 41316897, 2026). "The signature supports the role of APOE in lipid regulation through apolipoproteins and inflammation and includes, among others, neutrophil secreted granule proteins CAMP, CTSG, DEFA3, and MPO that point to inhibition of OLFM4 as a target for Alzheimer's disease therapeutics." (PMID 41316897, 2026).
asthma (2 papers, 2022). "It was characterized by the upregulation of genes related to neutrophils, such as OLFM4, which is produced by neutrophils and has been associated with asthma inflammation, and CTSG, the neutrophil protease cathepsin G, which has been involved in neutrophilic asthma." (PMID 35203504, 2022). "OLFM4 is regarded as a marker of asthma, septic shock, and many types of cancers." (PMID 36035204, 2022).
autoimmune disease (2 papers, 2023). A disorder resulting from loss of function or tissue destruction of an organ or multiple organs, arising from humoral or cellular immune responses of the individual to their own tissue constituents. "Another DEP was olfactomedin-4 (OLFM4), a glycoprotein expressed by immature myeloid cells and mature neutrophils, which has been proposed as a biomarker in several autoimmune diseases and cancers." (PMID 37529039, 2023).
colorectal tumor (2 papers, 2014 to 2016). "As previously reported, OLFM4 is highly represented in several library pools including colorectal tumour, bladder and intestine." (PMID 24495253, 2014).
endometrial adenocarcinoma (2 papers, 2014 to 2016). "We investigated OLFM4 expression in endometrium, analysed the association of OLFM4 with ER signalling in endometrial adenocarcinoma, and examined the roles of OLFM4 in endometrial adenocarcinoma." (PMID 24495253, 2014). "When we used bioinformatics tools to search for the genes contributing to gynecological cancers, the expression of Olfactomedin 4 (OLFM4) was found by digital differential display to be associated with differentiation of endometrial adenocarcinoma." (PMID 24495253, 2014). "When we searched for genes contributing to gynecological cancers through bioinformatics tools, we found OLFM4 to be associated with differentiation of endometrial adenocarcinoma." (PMID 24495253, 2014). "In an earlier study, preliminary data suggested that low-expression of OLFM4 correlated with poor differentiation of endometrial adenocarcinoma." (PMID 24495253, 2014). "The results suggested that OLFM4 expression was lower in less differentiated endometrial adenocarcinoma." (PMID 24495253, 2014). "Of these genes, OLFM4 was markedly down-regulated in poorly-differentiated endometrial adenocarcinoma compared with well-differentiated." (PMID 24495253, 2014). "We also investigated whether the expression of OLFM4 in endometrial adenocarcinoma cell lines is regulated by oestrogen receptor signalling." (PMID 24495253, 2014). "We further studied the effects of OLFM4 on biological features of endometrial adenocarcinoma cells." (PMID 24495253, 2014). "In contrast, OLFM4 over-expression suppressed proliferation and invasion of endometrial adenocarcinoma cells (data not shown)." (PMID 24495253, 2014).
endometrial carcinoma (2 papers, 2014 to 2016). A malignant tumor arising from the epithelium that lines the cavity of the uterine body. "Recent research has found OLFM4 to be highly expressed in proliferative-phase endometrium, and OLFM4 expression is associated with the presence of epidermal growth factor receptor-1 and oestrogen receptor-α (ERα) in endometriosis and endometrial cancer." (PMID 24495253, 2014). "In a previous study we demonstrated that knockdown of OLFM4 enhances the proliferation, migration, and invasion of endometrial carcinoma cells." (PMID 26871282, 2016). "It appeared that OLFM4 was involved in suppression of migration and invasion of endometrial carcinoma cells." (PMID 24495253, 2014). "The current study further supported a contribution of OLFM4 to differentiation of endometrial carcinoma." (PMID 24495253, 2014). "Olfactomedin 4 mRNA in Ishikawa, a well-differentiated human endometrial carcinoma cell line, was also higher than that in moderately-differentiated HEC-1B cells." (PMID 24495253, 2014). "In vitro studies demonstrated that ERα-mediated signalling regulated expression of OLFM4, and, in turn, OLFM4 suppressed proliferation, migration and invasion of endometrial carcinoma cells." (PMID 24495253, 2014). "The immunostaining of OLFM4 in endometrial cancer has been observed to be correlated with ERα staining." (PMID 24495253, 2014). "To confirm the in silico analysis, we assessed the expression of OLFM4 in normal endometrium, precancerous endometrial tissue and endometrial cancer using IHC." (PMID 24495253, 2014). "Our results showing OLFM4 to suppress migration and invasion by endometrial carcinoma cells support the suggestion that OLFM4 may function as a tumour suppressor during tumour progression." (PMID 24495253, 2014). "Moreover, ERα-mediated signalling regulated expression of OLFM4, and knockdown of OLFM4 enhanced proliferation, migration and invasion of endometrial carcinoma cells." (PMID 24495253, 2014). "However, the expression levels of OLFM4 in endometrial carcinomas were found comparable to those in healthy postmenopausal endometrium, although an increase of OLFM4 mRNA was observed in the eutopic endometrium of women with endometriosis compared with controls." (PMID 24495253, 2014). "Our results demonstrated that OLFM4 itself did not affect the apoptosis of endometrial carcinoma cells, but it may slightly inhibit cell proliferation." (PMID 24495253, 2014).
endometrioid adenocarcinoma (2 papers, 2014 to 2016). An adenocarcinoma characterized by the presence of malignant glandular epithelial cells resembling endometrial cells. "Low-expression of OLFM4 was associated with reduced cumulative survival rate of patients with endometrioid adenocarcinoma." (PMID 24495253, 2014). "Down-regulation of OLFM4 was associated with decreased cumulative survival rate of patients with endometrioid adenocarcinoma." (PMID 24495253, 2014). "Based on the expression traits of OLFM4 measured by IHC, we analysed the association of OLFM4 level with clinico-pathological features and prognosis of endometrioid adenocarcinoma." (PMID 24495253, 2014). "Expression of OLFM4 was increased during endometrial carcinogenesis, linked to the differentiation of endometrioid adenocarcinoma, and positively related to the expression of oestrogen receptor-α (ERα) and progesterone receptor." (PMID 24495253, 2014). "In the present study, intensive immunoreactivity for OLFM4 was observed in endometrioid adenocarcinoma, and its expression was linked to the level of differentiation of the tumour." (PMID 24495253, 2014). "Impairment of ERα-mediated OLFM4 expression promotes the malignant progression of endometrioid adenocarcinoma." (PMID 26871282, 2016). "In a previous study we demonstrated that impairment of estrogen receptor alpha (ERα)-mediated olfactomedin 4 (OLFM4) expression promotes the malignant progression of endometrioid adenocarcinoma, and we identified OLFM4 as a potential target of miR-486-5p." (PMID 26871282, 2016). "Immunostaining intensity of OLFM4 gradually decreased as the degree of differentiation declined in endometrioid adenocarcinomas." (PMID 24495253, 2014). "Our results, indicating that down-regulation of OLFM4 reduced the cumulative survival rate of patients with endometrioid adenocarcinoma, were consistent with these findings." (PMID 24495253, 2014). "Similar to what was observed with IHC, the OLFM4 mRNA level detected by real-time PCR in endometrial hyperplasia and endometrioid adenocarcinomas was higher than that in normal endometrium (P < 0.017)." (PMID 24495253, 2014). "The OLFM4 expression level in endometrioid adenocarcinoma was significantly higher than in normal endometrium (P = 0.008), indicating that OLFM4 expression is up-regulated in endometrial carcinogenesis." (PMID 24495253, 2014). "Expression of OLFM4 in endometrioid adenocarcinoma was positively correlated with the expression of ERα and PR." (PMID 24495253, 2014). "Expression of OLFM4 in endometrioid adenocarcinoma was positively related to expression of ERα and PR." (PMID 24495253, 2014). "Estrogen receptor signaling regulates the expression of OLFM4 in endometrioid adenocarcinoma." (PMID 26871282, 2016). "Our data suggested that impairment of ERα signal-mediated OLFM4 expression promoted the malignant progression of endometrioid adenocarcinoma, which may have significance for the therapy of this carcinoma." (PMID 24495253, 2014). "The rates of OLFM4 high-expression in normal endometrium, endometrial hyperplasia without or with atypia, and endometrioid adenocarcinoma were 43.3, 60.0, 66.7 and 68.0%, respectively." (PMID 24495253, 2014).
insomnia (2 papers, 2021 to 2025). A sleep disorder characterized by difficulty in falling asleep and/or remaining asleep. "We identified 62 variants linked to shared genetics of MDD and insomnia symptoms, with signals near MEIS1, RP11-6N13.1, OLFM4, HEXIM1, and TCF4 being the strongest." (PMID 34680902, 2021).
leukemia (2 papers, 2015). A malignant (clonal) hematologic disorder, involving hematopoietic stem cells and characterized by the presence of primitive or atypical myeloid or lymphoid cells in the bone marrow and the blood. "Overall, our studies indicate that OLFM4-mediated signaling supports the survival of primitive leukemia cells." (PMID 26561938, 2015). "The observed effect of OLFM4 knockdown on the LTC-ICs was different from the one we observed with less primitive leukemia cells, CFCs." (PMID 26561938, 2015). "The mechanisms responsible for the distinct role of OLFM4 in the survival of leukemia cells at different stages of maturation remain to be investigated." (PMID 26561938, 2015). "Using CML iPSC-derived primitive leukemia cells, we discovered olfactomedin 4 (OLFM4) as a novel factor that contributes to survival and growth of somatic lin−CD34+ cells from bone marrow of patients with CML in chronic phase, but not primitive hematopoietic cells from normal bone marrow." (PMID 26561938, 2015). "We validated this hypothesis by demonstrating the successful application of the iPSC-based platform to discover OLFM4 as a novel primitive leukemia cell survival factor in patients in the chronic phase of CML." (PMID 26561938, 2015). "Here, we advanced the iPSC model to study primitive leukemia cells and proved the utility of this model for discovering drug targets by identifying the novel CML LSC survival factor OLFM4." (PMID 26561938, 2015).
myeloid leukemia (2 papers, 2012 to 2015). A clonal proliferation of myeloid cells and their precursors in the bone marrow, peripheral blood, and spleen. "Moreover, up-regulated OLFM4 showed a strong anti-apoptotic activity in mouse lymphoid vein endothelial SVEC cells and human adenocarcinoma HeLa cells, whereas recent findings suggested a proapoptotic effect of OLFM4 in human myeloid leukemia HL-60 cells." (PMID 22471589, 2012). "However, a recent finding showed that OLFM4 has a proapoptotic effect in myeloid leukemia cells." (PMID 25970782, 2015).
ovarian serous adenocarcinoma (2 papers, 2016 to 2025). An adenocarcinoma that arises from the ovary and is characterized by the presence of malignant epithelial cells that, in well differentiated tumors, resemble the epithelium of the fallopian tube or, in poorly differentiated tumors, show anaplastic features and marked nuclear atypia. "Based on the expression of OLFM4 measured in paraffin-embedded tissues, we analyzed the association of OLFM4 expression with clinicopathological features and prognosis of ovarian serous adenocarcinoma." (PMID 26871282, 2016). "HO8910-pm and SKOV3 cells transfected with miR-486-5p mimics, had decreased OLFM4 mRNA levels, indicating that OLFM4 is a potential target of miR-486-5p in ovarian serous adenocarcinoma." (PMID 26871282, 2016). "In the current study, aberrant OLFM4 expression was observed in ovarian serous adenocarcinoma tissues." (PMID 26871282, 2016). "In contrast to ERα, miR-486-5p levels were inversely correlated with OLFM4 expression in ovarian serous adenocarcinoma." (PMID 26871282, 2016). "miR-486-5p expression was decreased in ovarian serous adenocarcinoma as compared to normal ovary, and inversely correlated with OLFM4 expression in ovarian serous adenocarcinoma." (PMID 26871282, 2016). "Additionally, miR-486-5p targets OLFM4, a gene whose downregulation in ovarian serous adenocarcinoma tissues contributes to enhanced proliferation, migration, and invasion of OC cells." (PMID 39859407, 2025). "In this study we investigated the role of OLFM4 in ovarian serous adenocarcinoma." (PMID 26871282, 2016). "We therefore sought to investigate the effects of OLFM4 on ovarian serous adenocarcinoma cells." (PMID 26871282, 2016). "Ovarian serous adenocarcinoma tissues had reduced OLFM4 expression." (PMID 26871282, 2016). "Thus, estrogen receptor signaling in the development of ovary serous adenocarcinoma may be partially due to the regulation of OLFM4." (PMID 26871282, 2016). "Expression of OLFM4 in ovarian serous adenocarcinoma was positively correlated with the expression of ERα but not PR." (PMID 26871282, 2016).
pancreatic ductal adenocarcinoma (2 papers, 2014 to 2020). An infiltrating adenocarcinoma that arises from the epithelial cells of the pancreas. "However, it has been reported that, in pancreatic ductal adenocarcinomas, OLFM4 expression was up-regulated in the poor-prognosis group, and high expression of OLFM4 correlated significantly with lower overall survival." (PMID 24495253, 2014).
prostate adenocarcinoma (2 papers, 2015). "In this study, we found that Olfm4-knockout mice developed prostatic intraepithelial neoplasia and prostatic adenocarcinoma." (PMID 26581960, 2015). "Histological and immunohistochemical evaluation of DLP tissue from 20-month-old Olfm4-knockout mice revealed that the tumor type that developed in the Olfm4-knockout mice was androgen receptor (AR)-positive prostatic adenocarcinoma." (PMID 26581960, 2015). "It is of interest that OLFM4 was demonstrated in benign prostate tissue, but not in prostate adenocarcinomas." (PMID 26416558, 2015).
prostate tumor (2 papers, 2017 to 2022). "They discovered that the Hedgehog signalling pathway was significantly upregulated with Olfm4-knockout, and the loss of Olfm4 promoted progression of prostatic neoplasms." (PMID 35390003, 2022). "OLFM4 was shown to be an important regulator of apoptosis in murine prostate tumor cells." (PMID 28767721, 2017).
acute graft versus host disease (1 paper, 2020). A syndrome of immunologically mediated tissue damage that may occur following an allogeneic transplant, usually affecting the skin, liver, and GI tract. "Fold change in absolute number of OLFM4+ neutrophils from baseline to week of clinical changes was associated with AKI and acute graft versus host disease, however, when changes in ANC were included in logistic regression, neither of these associations remained (lower)." (PMID 32470072, 2020).
acute myeloid leukemia (1 paper, 2015). Acute myeloid leukemia (AML) is a group of neoplasms arising from precursor cells committed to the myeloid cell-line differentiation. "It has been shown that OLFM4 expression is upregulated in a subset of patients with acute myeloid leukemia and primary myelo-fibrosis." (PMID 26561938, 2015).
amyotrophic lateral sclerosis (1 paper, 2024). Amyotrophic lateral sclerosis (ALS) is a neurodegenerative disease characterized by progressive muscular paralysis reflecting degeneration of motor neurons in the primary motor cortex, corticospinal tracts, brainstem and spinal cord. "The specific numeric expression data chosen for this example are the mRNA abundance levels of the OLFM4 and LOC440742 genes from an RNA-seq experiment of human cerebellum and frontal cortex tissues with or without amyotrophic lateral sclerosis (ALS)." (PMID 38312938, 2024).
breast tumors (1 paper, 2023). "Furthermore, the expression of olfactomedin-4 (OLFM4) is higher in non-invasive breast tumors than in invasive breast cancer." (PMID 38169859, 2023).
cervical intraepithelial neoplasia (1 paper, 2014). "OLFM4 expression and distribution was tested by IHC and RT-PCR on cervical intraepithelial neoplasia (CIN) and invasive SCC." (PMID 28250389, 2014).
chronic granulomatous disease (1 paper, 2022). Chronic granulomatous disease (CGD) is a rare primary immunodeficiency, mainly affecting phagocytes, which is characterized by an increased susceptibility to severe and recurrent bacterial and fungal infections, along with the development of granulomas. "OLFM4 deletion enhanced immune response against S. aureus in mice with the chronic granulomatous disease, and OLFM4 may be a critical target for the augmentation of the host defense system against bacterial infection." (PMID 36035204, 2022).